DLG2 (discs large MAGUK scaffold protein 2)
Diseases named in the same sentence as DLG2 in open-access papers (continued):
Sharing a sentence is not in itself a finding about the gene and the disease.
renal oncocytoma (2 papers, 2006 to 2023). "The new isoform of DLG2 is the promising candidate gene for molecular differential diagnostics of renal oncocytoma." (PMID 16640776, 2006). "The new isoform is specifically upregulated in renal oncocytoma, whereas the known DLG2 gene is downregulated in this type of kidney tumour." (PMID 16640776, 2006).
squamous carcinoma (2 papers, 2021). "It was found that in 2,616 coding genes, 2 or more integration sites presented among samples, like RAD51B, MACROD2, FHIT, CSMD1, LRP1B, and DLG2, which had already been previously reported as frequent sites of integration in squamous carcinoma samples." (PMID 33810183, 2021). "Squamous cell carcinoma (2/2) showed high DLG2 expression with low LIN7A expression." (PMID 33726762, 2021). "Squamous cell carcinoma (2/2) clustered with high DLG2 expression and low LIN7C expression." (PMID 33726762, 2021).
Stroke (2 papers, 2023 to 2025). Sudden impairment of blood flow to a part of the brain due to occlusion or rupture of an artery to the brain. "Investigations of PKP4, DLG1, DLG2, PTPRS and OBSL1 found insufficient evidence to provide a direct link between these genes and neurodegenerative or stroke events." (PMID 37422595, 2023). "Overall, the studies analyzed in this systematic review consistently highlight the translational potential of touchscreen platforms for cognitive assessment across human and rodent models in conditions such as DLG2 CNV deletions, OCD, HD, stroke and pharmacological intervention." (PMID 41236438, 2025).
ulcerative colitis (2 papers, 2022 to 2025). An inflammatory bowel disease involving the mucosal surface of the large intestine and rectum. "Expression of Dlg2 is downregulated in inflammatory gastrointestinal conditions, such as ulcerative colitis, suggesting a regulatory role of Dlg2 in inflammatory response." (PMID 39954235, 2025). "In the ulcerative colitis (UC) patient data, in accordance with previous literature, NFKBIZ was upregulated in UC patients and even more in active UC cases, whereas we could show that DLG2 was downregulated." (PMID 35499706, 2022).
adenoma (1 paper, 2022). A neoplasm arising from the epithelium. "In this study we showed that DLG2 was downregulated in human colon tumor tissue with the lowest DLG2 level seen in larger size adenomas, and that silencing of DLG2 caused an increase in colon cancer cell proliferation in vitro." (PMID 35499706, 2022). "Using publicly available microarray colon adenoma data (GSE8671) we determined the expression of DLG2 relative to adenoma size." (PMID 35499706, 2022). "DLG2 was downregulated in IBD (log2 FC = 0.81, p < 0.05), adenoma (log2 FC = 1.1, p < 0.1) and colon cancer (log2 FC = 1.3, p < 0.01)." (PMID 35499706, 2022).
anxiety disorder (1 paper, 2022). A category of psychiatric disorders which are characterized by anxious feelings or fear often accompanied by physical symptoms associated with anxiety. "DLG2 haploinsufficiency is related to NDDs, with a wide clinical spectrum, ranging from ID, ASD, and ADHD to psychiatric disorders such as mood disorders, anxiety disorders, OCD, ODD, and even eating disorders." (PMID 35627244, 2022).
atherosclerosis (1 paper, 2025). A disease characterized by the build-up of fatty material and calcium deposition in the arterial wall resulting in partial or complete occlusion of the arterial lumen. "Only one locus, rs472784 in DLG2 (P = 2.0×10−9), from the CAD-CIMT analysis was novel for atherosclerosis." (PMID 40313769, 2025).
colon adenoma (1 paper, 2022). An adenoma that arises from the colon. "We could also show that DLG2 expression decreased as colon adenoma size increased to 1.1–1.5 cm and larger than 1.5 cm when compared to tumors under 1 cm in diameter (Log2 fold change = 1.32, p < 0.01 and Log2 fold change = 1.32, p < 0.01)." (PMID 35499706, 2022).
colon cancer (1 paper, 2022). "The overexpression and silencing of DLG2 in colon cancer cells were used to determine the effect of DLG2 expression on the activation of the inflammasome and subsequent cytokine release." (PMID 35499706, 2022). "The DLG2 expression levels were established in publicly available inflammation, colon cancer and mouse model datasets." (PMID 35499706, 2022). "We have been able to confirm in colon cancer cells that increased DLG2 results in an increase in BAX and a decrease in BCL2 resulting in lower cell proliferation." (PMID 35499706, 2022). "Here we show that DLG2 is downregulated in inflammatory bowel diseases such as UC as well as colon cancers, indicating that DLG2 alteration occurs early in the tumorigenesis process." (PMID 35499706, 2022). "So far, there is no data that clearly elucidates this role, and this study was designed to investigate DLG2 in inflammatory colon disease and in colon cancer as well as its impact on inflammasome induction." (PMID 35499706, 2022). "DLG2 expression is altered in response to inflammation in the gut as well as colon cancer, resulting in altered ability to form inflammasomes." (PMID 35499706, 2022). "To test if DLG2 influenced these pathways we investigated the phosphorylation levels of AKT, FOXO3 and S6 in colon cancer cells." (PMID 35499706, 2022). "In light of the building body of evidence that DLG2 is an important tumor suppressor gene we here investigate DLG2 and NFKBIZ and their impact on the inflammasome induction in inflammatory colon disease and in colon cancer." (PMID 35499706, 2022). "Additionally, DLG2 overexpression in THP-1 cells resulted in an altered cytokine and growth factor profile which was subsequently used to treat colon cancer cells decreasing the number in G2/M cell cycle phase." (PMID 35499706, 2022).
colorectal adenoma (1 paper, 2015). An adenoma that arises from the colon or rectum. "Most interestingly, in the Gaspar Colon colorectal adenoma dataset Bcl6 expression was significantly positively correlated with MAPK9, MAP2K4 and Yes1, and negatively with Dlg2, relative to normal intestinal mucosa." (PMID 26187947, 2015).
dementia (1 paper, 2022). Loss of intellectual abilities interfering with an individual's social and occupational functions. "A common variant in DLG2, rs683250, was previously associated with increases of shape asymmetry in controls as compared to individuals with dementia." (PMID 35246634, 2022).
Fanconi anemia (1 paper, 2020). Fanconi anemia (FA) is a hereditary DNA repair disorder characterized by progressive pancytopenia with bone marrow failure, variable congenital malformations and predisposition to develop hematological or solid tumors. "Gene set enrichment analysis of the genes correlating to DLG2 in the selected data sets showed that the pathways; cell cycle (p < 0.0001), DNA replication (p < 0.0001), Fanconi anemia (p < 0.0001) and mismatch repair (p < 0.0001) were enriched in the three analyzed NB primary datasets." (PMID 32312269, 2020).
gastric cancer (1 paper, 2026). A primary or metastatic malignant neoplasm involving the stomach. "Transcriptomic analysis demonstrated significant downregulation of DPP6 and DLG2, while KDM4D, USP34, and VDR were significantly upregulated in gastric cancer tissues compared with normal controls." (PMID 42195053, 2026).
hyperglycaemia (1 paper, 2020). "FDM-risk variants within these selective sweeps identified GRM5 and DLG2 as candidates for beta cell dysregulation, as both are involved in glucose-stimulated insulin secretion and hyperglycaemia susceptibility in rodent and human." (PMID 33154479, 2020).
inflammatory bowel disease (1 paper, 2022). A spectrum of small and large bowel inflammatory diseases of unknown etiology. "Restoration of DLG2 in the colon may provide a mechanism for improved immunotherapy function as well as attenuating inflammatory bowel diseases." (PMID 35499706, 2022).
Insulin resistance (1 paper, 2019). Increased resistance towards insulin, that is, diminished effectiveness of insulin in reducing blood glucose levels. "MYO5B, DLG2, RHOU, and SNCA are novel biomarkers for the development of insulin resistance." (PMID 30678306, 2019).
liver fibrosis (1 paper, 2024). "These genes, including Robo1, Gabrb3, Gpc6, Ephb2 and Dlg2, are usually not expressed in healthy liver, and were reported to be upregulated in metabolic dysfunction-associated steatohepatitis and liver fibrosis." (PMID 39456836, 2024).
migraine (1 paper, 2019). "The associations of six SNPs identified from our previous study, including TRPM8 rs10166942, LRP1 rs1172113, DLG2 rs655484, GFRA1 rs3781545, UPP2 rs7565931, and GPR39 rs10803531, and migraine endophenotypes, including chronic migraine and allodynia were tested." (PMID 31842742, 2019).
preeclampsia (1 paper, 2018). Preeclampsia is a hypertensive disorder of pregnancy that is characterized by new-onset hypertension with proteinuria presenting after 20 weeks of gestation, and depending on mild or severe forms may initially present with severe headache, visual disturbances, and hyperreflexia. "The DLG2 gene is previously reported differentially expressed in transcripts of decidua basalis in preeclampsia." (PMID 29758065, 2018). "Based on these findings, we cannot rule out a possible role of the MTHFR, ITPR1, and DLG2 gene variants for risk of developing preeclampsia." (PMID 29758065, 2018).
renal tumours (1 paper, 2006). "In course of a project of gene expression profiling in different types of renal tumours with Affymetrix microarray hybridization and semiquantitative RT-PCR we have identified a novel isoform of DLG2 gene upregulated exclusively in RO." (PMID 16640776, 2006).
retinitis pigmentosa (1 paper, 2024). Retinitis pigmentosa (RP) is an inherited retinal dystrophy leading to progressive loss of the photoreceptors and retinal pigment epithelium and resulting in blindness usually after several decades. "Again, in our study, DLG2 was found to be differentially expressed in the fovea, making involvement in the pathophysiology of retinitis pigmentosa less likely." (PMID 39337590, 2024).
Sinus bradycardia (1 paper, 2021). Bradycardia related to a mean resting sinus rate of less than 50 beats per minute. "Interestingly, CTNNA3, having a strong correlation with sinus bradycardia backed up by our previous analysis, also interacted with DLG2 through circumstantial evidences." (PMID 33914752, 2021). "Therefore, all three genes DLG2, CATSPERB and RYR3 may not serve as susceptibility genes of sinus bradycardia induced by SGAs." (PMID 33914752, 2021).
Smith-Magenis syndrome (1 paper, 2021). Smith-Magenis syndrome (SMS) is a complex genetic disorder characterized by variable intellectual deficit, sleep disturbance, craniofacial and skeletal anomalies, psychiatric disorders, and speech and motor delay. "These include a region located within the MHC, another located on chromosome 17 containing DLG2, TOM1L2, and overlapping the Smith-Magenis syndrome deletion, and another on chromosome 16 containing CENPT and PRMT7." (PMID 33646943, 2021).
tumor (29 papers, 2006 to 2025). "Glioma-derived exosomes (GM-Exos) induce the conversion of normal human astrocytes to tumor-associated astrocytes via the miR-3065-5p/DLG2 signaling axis and promote malignant tumor progression." (PMID 38890722, 2024). "Loss of expression of DLG2 has been identified in a number of cancers to contribute to the disease by resulting in increased tumor cell proliferation and poor survival." (PMID 35499706, 2022). "Discs large homolog 2 (DLG2) was highly mutated in both human and dog, and was validated as a tumor suppressor through a workflow that spanned human and canine cell lines, and a clinically relevant murine model of OS." (PMID 30093633, 2019). "Meanwhile, Discs large homolog 2 (DLG2), a member of the membrane-associated guanylate kinase family that regulates cell polarity and interacts with the Hippo signaling pathway, has been implicated as a potential tumor suppressor." (PMID 41256331, 2025). "Similarly, down-regulation of DLG2 could reverse the reduced expression of oncogenetic downstream signaling and increased expression of tumor suppressive downstream signaling caused by miR-6836 down-regulation." (PMID 37416779, 2023). "We also analyzed the effect of DLG2 overexpression on tumor tumorigenesis through a xenograft mouse model assay." (PMID 39856747, 2025). "The results showed that the treatment with DLG2 overexpression led to a delayed growth of tumors and a decrease in tumor weight." (PMID 39856747, 2025). "In different cellular environments, DLG2 can either inhibit tumor formation or promote tumorigenesis." (PMID 39856747, 2025). "Notable candidate genes included ANKH (12 associated SNPs), EIF6 (11 SNPs), and SLC4A7, DLG2, and FBXL7, which are widely implicated in cellular inflammation, immune response, and tumor development." (PMID 40427243, 2025). "To further explore the molecular mechanism of miR-6836 by targeting DLG2, we examined the expression level of the reported downstream signaling of DLG2 by western blot based on the published mechanism of DLG2 as a tumor suppressor gene 27-28." (PMID 37416779, 2023). "DLG2 is an important tumor suppressor gene, and DLG2 overexpression leads to an increase in the expression of IκBζ." (PMID 37377955, 2023). "Our analysis showed that these previously established tumor types in which LIN7A is oncogenic or disruptive tended to cluster with low DLG2 expression." (PMID 33726762, 2021). "The DLG2 gene resides in the 11q-deleted region, thus makes it an interesting NB candidate tumor suppressor gene." (PMID 32312269, 2020). "To make the case that DLG2 is the tumor suppressor located in 11q we set forth a criteria based on what is currently known about the clinical and molecular features of deletion of 11q in NB." (PMID 32312269, 2020). "CtDNA from Patient F contained one SNV in the ATRX gene (3.53% of reads) and one SNV in the DLG2 gene (0.79% of reads) that matched tumor specific aberrations." (PMID 29560102, 2018). "In vivo, DLG2 overexpression was shown to reduce tumor formation." (PMID 39856747, 2025). "This work builds on the growing body of evidence that DLG2 functions as a tumor suppressor." (PMID 35499706, 2022). "DLG2 expression in the tumor tissue was lower than the paired mucosa sample (Log2 fold change = 1.89, p < 0.001), as well as the paired ascending and descending colon mucosa from the distal healthy colon tissue (Log2 fold change = 1.36, p < 0.05, Log2 fold change = 1.32, p < 0.05, respectively)." (PMID 35499706, 2022). "Cross-species genomics identified DLG2 as a tumor suppressor in OS." (PMID 33520450, 2021). "In addition to considering the loss of DDR factors, which decrease genomic integrity, it is clear that tumor suppressors, such as DLG2, are also influenced by oncogenic signaling activity." (PMID 34885007, 2021). "Whereas the function of KIAA00825 is unknown, DLG2 belongs to the PDZ discs—large polarity protein family which have shown both tumour suppressive as well as oncogenic properties." (PMID 34187875, 2021).
tumor (continued). "Moreover, DLG2 has been shown to have tumor suppressor function." (PMID 35418124, 2022). "Several tumor suppressor genes located on chromosome 11q, such as DLG2 and ATM, are frequently lost or repressed in NB, contributing to tumor progression." (PMID 41228232, 2025). "The results of IHC indicated that tumor generated from Lv-miR-6836 cells had higher PCNA and lower DLG2 expression." (PMID 37416779, 2023). "The Discs Large MAGUK Scaffold Protein 2 (DLG2) gene was recently reported to regulate the differentiation phenotype induced by ATRA, and proposed as a tumor suppressor candidate in NB." (PMID 35850708, 2022). "In the 20 cases analyzed, we detected three fusion events in known cancer driver genes (ATM in LUSC2; PTEN in LUSC1; WHSC1 in LUSC1), and a further seven events in candidate tumor-suppressor genes, including BOD1, DLG2, MBD2, and RBL1." (PMID 30348992, 2019). "A positive relationship (Y = 0.97x + 0.04, p < 0.0001) between DLG2 and LIN7C between tumor datasets could be confirmed." (PMID 33726762, 2021). "A positive relationship (Y = 0.82x–0.05, p < 0.001) between DLG2 and LIN7A across tumor datasets could be confirmed." (PMID 33726762, 2021). "A positive relationship (Y = 0.70x + 0.07, p < 0.0001) could be established between DLG2 and LIN7B across tumor datasets." (PMID 33726762, 2021). "We could also see that expression of DLG2 was inversely correlated with MYCN status and tumor stage." (PMID 32312269, 2020). "In addition, genes such as DLG2 and FBXL7 are involved in tumor progression and immune regulation." (PMID 40427243, 2025).
psychiatric disorder (13 papers, 2014 to 2025). A disorder characterized by behavioral and/or psychological abnormalities, often accompanied by physical symptoms. "The lack of effects in the other behavioural task carried out also suggest a relatively specific and subtle behavioural impairment in this genetic model of psychiatric disorder risk due to haploinsufficiency of Dlg2." (PMID 37705179, 2023). "In this paper, we present data indicating heterozygosity of Dlg2, which has been previously associated with a number of psychiatric diseases, results in selective behavioural deficits similarly associated with disease in Dlg2+/− mice." (PMID 35118804, 2022). "Although DLG2 has been linked to psychiatric disorders, our work now describes a cohort of patients with DLG2 deletions who present three phenotypic categories of NDDs: cognitive, behavioral, and psychiatric." (PMID 28724449, 2017). "Genetic variation in the DLG2 locus has been associated with a variety of psychiatric disorders." (PMID 38281050, 2024). "Variations in the Dlg2 gene have been linked to increased risk for psychiatric disorders." (PMID 37705179, 2023). "The DLG2 gene locus is linked to multiple psychiatric disorders." (PMID 35075790, 2022). "So far, human CNV deletions in DLG2 have been linked to psychiatric disorders." (PMID 28724449, 2017). "Shared genetic pathways among synaptopathies including psychiatric disorders have been related to DLG2 haploinsufficiency both in mice models and in human studies." (PMID 35627244, 2022). "This suggests functional behavioural and cognitive domains associated with long‐term adaptation to the environment that also depend on specific long‐term plasticity mechanisms are particularly sensitive to haploinsufficiency of DLG2 across psychiatric disorders." (PMID 35118804, 2022). "Our findings suggest a crucial role for DLG2/PSD-93 in the regulation of striatum-related circuitries, shedding a light on the potential involvement of striatal dysfunction in the pathology of various psychiatric disorders accompanying disruption of the Dlg2 gene." (PMID 35966008, 2022).
cancer (12 papers, 2006 to 2025). A tumor composed of atypical neoplastic, often pleomorphic cells that invade other tissues. "The regulatory network analysis showed the association of some important hub proteins like GSK3B, NUMB, PEG3, ITGA2 and DLG2 with cancer-associated pathways." (PMID 28587194, 2017). "It has been reported that DLG2 participated in cancer progression." (PMID 39856747, 2025). "Furthermore, upregulation of dvl2 and dlg2 expression has been found in various forms of cancer as shown in the COSMIC database." (PMID 27536874, 2016). "Furthermore, in the Rohrbeck Lung (all-Lung, cancer only) dataset Bcl6 expression was positively correlated with MAP2K4, Yes1 and negatively correlated with Dlg2 and Lgl1." (PMID 26187947, 2015). "The conventional isoform of DLG2 gene is down-regulated in RO only, whereas the difference between the normal kidney and the carcinomas is statistically non-significant." (PMID 16640776, 2006).